IL6 (interleukin 6)
Diseases named in the same sentence as IL6 in open-access papers (continued):
Sharing a sentence is not in itself a finding about the gene and the disease.
breast cancer (continued). "IL6 silencing strongly suppresses in vitro anchorage-independent colony formation and in vivo tumor formation and growth of basal breast cancer cells." (PMID 35682546, 2022). "In this regard, it has been shown that IL-6 stimulated the proliferation and migration of breast cancer cells." (PMID 35406622, 2022). "Knockdown of MnSOD inhibits TNBC cell invasion, breast cancer stem cells (BCSCs), mROS, and IL-6 excretion promoted by MCT-1." (PMID 35017469, 2022). "Recently, the fact that IL-6-mediated Jagged1/Notch signaling pathway enhanced the ability for breast cancer cells metastasis has been demonstrated." (PMID 35924148, 2022). "In breast cancer, IL-6 expression correlates with poor patient survival, promotes growth and invasion, and mediates metastatic progression, which identifies the IL-6 signaling axis as a potential therapeutic target." (PMID 35371975, 2022). "The exposure of different subtypes of breast cancer cells to an inflammatory cytokine, interleukin 6 (IL-6), induced epithelial–mesenchymal transition and enhanced tissue invasion." (PMID 35208277, 2022). "Circulating FABP4 functions as a tumor-promoting factor for obesity-related breast cancer through the IL-6/STAT3/ALDH1 pathway." (PMID 36060264, 2022). "Overall, these findings suggested that breast cancer cells induce IL-6 expression in tumor activated macrophages via p-38 signaling." (PMID 35300689, 2022). "The finding that IL-6 mRNA underwent m6A modification prompted us to examine if IL-6 production positively correlated with nuclear METTL3 abundance in a panel of human breast cancer cell lines." (PMID 36289222, 2022). "Taken together, these findings demonstrate that TAM derived IL-6 enhances the CSC phenotype in breast cancer cells through STAT-3 pathway." (PMID 35300689, 2022). "Modern studies have shown that this drug pairs can increase interleukin-6 (IL-6) level in breast cancer model mice, inhibit the proliferation and promote the apoptosis of breast cancer cells." (PMID 35814234, 2022). "YAP has been shown to promote breast cancer stemness by upregulating CSC-associated genes and IL-6 through serum response factors." (PMID 35413945, 2022). "In breast cancer, the most studied members of this family are interleukin-6 (IL-6), leukemia inhibitory factor (LIF), oncostatin M (OSM), and interleukin-11 (IL-11)." (PMID 35163731, 2022). "In 2017, sera from 110 breast cancer patients were collected and evaluated for serum levels of sonic hedgehog (Shh) and IL-6 independently of their progesterone, estrogen or HER2 status." (PMID 35818030, 2022). "Adipose-induced EMT in breast cancer cells can be reversed by inhibition of the IL-6/STAT3 signaling axis, by using U.S. food and drug administration (FDA)-approved anthelmintic niclosamide." (PMID 35701840, 2022). "Intriguingly, it was reported that GPX8/IL6/STAT3 axis was important for maintaining aggressive phenotype in breast cancer." (PMID 35978854, 2022). "IL-6 and IL-8 expression are described as the first step of tumor progression and metastasis in breast cancer, and their levels are related to the disease stage of breast cancer patients." (PMID 36499741, 2022). "Both clinical and preclinical studies have reported that IL-6 and IL-11 released from breast cancer cells contributed to the development of bone metastasis." (PMID 35428832, 2022). "The significant differences in breast cancer patients were p = 0.0013 (IL-6) and p = 0.0026 (IL-8) compared to colorectal cancer patients and p < 0.0001 (IL-6) and p = 0.0004 (IL-8) compared to pancreatic patients." (PMID 36139592, 2022). "Meanwhile, IL-6 was also important as IL-8 for the progression of breast cancer cells, and the expression and release of IL-6 and IL-8 were regulated via MAPK and NF-κB mediated." (PMID 35053925, 2022). "In pancreatic cancer, FGF seems to drive cancer dissemination, and in breast cancer, IL-6 and IL-8 released by senescent fibroblasts increase invasiveness in several cell lines." (PMID 36497411, 2022).
breast cancer (continued). "The lowest IL-6 and IL-8 cytokine levels were found in breast cancer patients and showed a significant difference compared to the other groups, although non-significant in relation to controls." (PMID 36139592, 2022). "However, high concentrations of some proteins involved in inflammation, such as interleukin-6 (IL-6) and interleukin-8 (IL-8), or in angiogenesis, such as angiopoietin-like proteins, have been shown to be associated with a high risk of metastatic progression of breast cancer." (PMID 35818030, 2022). "Most existing studies on the effects of exercise on inflammatory factors and IGF systems in breast cancer survivors examine IL-6, IL-10, IL-1β, TNF-α, CRP, IGF-1, and IGFBP-3 levels." (PMID 36482346, 2022). "IL-6 (ORper standard deviation (SD) = 1.33 (1.11–1.60)) and TNF-α (ORper SD = 1.32 (1.11–1.58)) were positively associated with breast cancer risk in fully adjusted models." (PMID 35948877, 2022). "Here, we observed enhanced expression of CSC specific markers, Sca-1 and ALDH1 which was abrogated in breast cancer cells when IL-6 was neutralized in the CM of activated RAW264.7 cells." (PMID 35300689, 2022). "Inflammatory cytokines including interleukin-6 (IL-6) play essential roles in breast cancer metastasis." (PMID 35743249, 2022). "In the present study, we have delineated the signalling mechanism through which breast cancer cells induce IL-6 production in TAMs." (PMID 35300689, 2022). "Clinically, cytoplasmic staining of IL-6Rα is significantly correlated with tamoxifen resistance in ER+ breast cancer patients suggesting IL-6/JAK/STAT3 is an actionable therapeutic target to sensitize tumor cells to current SOC treatment." (PMID 35371975, 2022). "IL-6 is not only expressed and secreted by breast cancer cells, but also by diverse cell types that are part of the tumor microenvironment, such as myeloid-derived suppressor cells (MDSCs), fibroblasts, lymphatic endothelial cells, and adipocytes." (PMID 35163731, 2022). "IL-6 has also been shown to promote osteolytic metastasis of breast cancer by stimulating osteoclastogenesis, and neutralization of IL-6 was sufficient to prevent this occurrence." (PMID 35775492, 2022). "The adipocyte-derived IL-6 was reported to promote breast cancer metastasis by inducing PLOD2 expression through activating the JAK/STAT3 and PI3K/AKT signaling pathways." (PMID 35924148, 2022). "In conclusion, we herein provide direct evidence that breast cancer cells educate macrophages towards tumor promoting phenotype by inducing IL-6 expression through p38-MAPK pathway." (PMID 35300689, 2022). "The expression of IL-6 is increased by TDEVs in breast cancer, lung cancer, and melanoma in various ways." (PMID 36405712, 2022). "Core fucosylation of these molecules plays important functions in breast cancer cell adhesion to vitronectin, and their responsiveness to IL-6 or OSM signaling is involved in breast cancer EMT and metastasis." (PMID 35303925, 2022). "Because STAT3 is constitutively active in the majority of breast cancers and plays an important role in mediating breast cancer growth, migration, and metastasis, this review will focus on the IL-6/JAK/STAT3 signaling cascade." (PMID 35371975, 2022). "Interleukin 6 (IL-6) increases the invasive ability, metastatic potential, and stem-like phenotype of breast cancer cells." (PMID 35745583, 2022). "Studies have shown that dapansutrile can inhibit the IL6/STAT3 axis to inhibit breast cancer metastasis." (PMID 36105284, 2022). "The gene-disease interaction network suggests the potential role of CXCL8, NOS2, and IL-6 in mediating mammary neoplasms, inflammation, hyperalgesia, cholestasis, and neoplastic cell transformation." (PMID 35720847, 2022). "Multiple mechanisms mediate IL-6-induced breast cancer progression, such as activation of autocrine/paracrine loops under inflammatory conditions and IL-6’s impact on the surrounding tumor microenvironment." (PMID 35371975, 2022).
breast cancer (continued). "We further corroborated our findings in clinical settings by correlating the expression of the TAMs specific genes and IL-6 in breast cancer clinical specimens using TCGA datasets." (PMID 35300689, 2022). "Only the EPIC-Varese study also reported results for IL-6 and TNF-α among premenopausal women and noted a higher breast cancer risk with increasing levels of IL-6 [RR1SD = 1.58 (1.02–2.46)] and TNF-α [RR1SD=1.81 (0.91–3.61)]." (PMID 35430795, 2022). "The prognostic impacts of preoperative IL-6 expression levels in patients with breast cancer remain controversial." (PMID 35924148, 2022). "Treatment with SB203580 resulted in abrogation of enhanced IL-6 expression in macrophages in response to CM of breast cancer cells as confirmed by in vitro studies." (PMID 35300689, 2022). "Serum IL-6, IL-17, and VEGF are strongly associated with breast cancer development and can be used as a reference indicators for breast cancer diagnosis." (PMID 36531035, 2022). "Administration of Bcl-2 antagonist, sabutoclax, concurrently suppresses IL-6/STAT3 signaling to resensitize chemoresistant breast cancer cells to chemotherapeutic agents." (PMID 35371975, 2022). "Our findings suggest that the IL-6-pSTAT3-ZEB1-DNMT1 axis plays a key role in TAM-induced breast cancer growth and metastasis." (PMID 36273188, 2022). "We found that the mRNAs of the pro-inflammatory molecules Cxcl10 and IL-6 were upregulated in both cell types, while TNFα mRNA was upregulated only in mammary carcinoma cells when cells were transfected with poly(I:C)." (PMID 35737804, 2022). "After poly(I:C) transfection, the levels of protein expression of IFNβ and IL-6 on mammary carcinoma cells were significantly upregulated." (PMID 35737804, 2022). "IL6, one of the proinflammatory cytokines, promoted breast cancer growth and metastasis through IL6/JAK/STAT3 loop." (PMID 33593435, 2021). "Higher levels of IL-6 have been found in overweight and obese women with IR and early-stage breast cancer." (PMID 34681797, 2021). "IL-6 was reported to induce Snail and Twist in a panel of oestrogen receptor-positive (ER+) human breast cancer cells in vitro, while only Twist levels were increased in xenografts generated by MCF7 cells ectopically expressing IL-6." (PMID 34361105, 2021). "Further study has demonstrated that in a mouse model of breast cancer, MDSCs secreted IL-6 at the tumor site, thus inducing PSTAT3 expression by tumor cells and promoting tumor progression and metastatic potential." (PMID 34527668, 2021). "Senescent mesenchymal stem cells stimulate proliferation and migration of breast cancer cells in vitro and promote tumor progression in xenograft mice by activating IL-6/STAT-3 signaling pathway." (PMID 34458273, 2021). "Serum NF-κB, TNF-α, sTRAIL, IL-6, PTX-3, PCT, and serum CRP levels were measured using enzyme-linked immunosorbent assay (ELISA) in 40 patients with breast cancer, 40 patients with colon cancer and 30 healthy controls." (PMID 33776564, 2021). "Silencing RORα in S1 cells and MCF-10A cells increased the IL-6 protein levels in the conditioned medium, while overexpression of RORα decreased the level in breast cancer cells." (PMID 34639006, 2021). "For example, elevated levels of IL-6 stimulate hyperactivation of JAK/STAT3 signaling, which is often associated with poor patient outcomes in colorectal cancer, breast cancer, oral cancer, and myeloma." (PMID 34422643, 2021). "IL-6, secreted mainly by immune cells, such as macrophages from obese adipose tissues or breast cancers, stimulates the synthesis of estrogen by activating aromatase as well as enhancing its gene transcription." (PMID 35008370, 2021). "For instance, in breast cancer, IL6 release after treatment converts differentiated tumor cells to cancer stem cells through the IL6-JAK1-STAT3 pathway." (PMID 34447383, 2021). "In both ER-positive (MCF-7) and MDA-MB-231 TNBC cell lines, IL-6 promotes invasion and migration of the breast cancer cells." (PMID 34944905, 2021).
breast cancer (continued). "In a coculture milieu of breast cancer cell lines and adipocytes, the expression and secretion of IL-6 leads to an increase in the metastatic potential of cancer cells by the upregulation of PLOD2 expression." (PMID 34202411, 2021). "Overexpression of lncRNA-AU021063 in breast cancer cells prolonged the activation of the Mek1/2 and Erk1/2 kinases and increased the production of Trib3 protein under IL6 signaling." (PMID 35126382, 2021). "For example, inflammation and progression of breast cancer and the elevation of forming breast cancer stem cells are mediated through the IL-6/STAT3/ROS pathway." (PMID 34488773, 2021). "Directly stimulating oestrogen-receptor-positive breast cancer cells with IL-6 has been shown to reduce cell growth in vitro." (PMID 33864493, 2021). "IL-6 is involved in various oncogenic activities (cell proliferation, cell survival, migration, invasiveness and resistance towards anticancer therapy), therefore making IL-6 signaling cascades in breast cancer a target of choice." (PMID 34445170, 2021). "In transformed breast cells, IL-6 reduces the expression levels of let-7 by activating Lin28 transcription via the NF-κB pathway, leading to the development of breast cancer and enhanced CSC characteristics." (PMID 34722553, 2021). "Analysis of transcriptomic and genomic data revealed that the expression of lncRNA-AU021063 was significantly upregulated in IL6-stimulated 4T1 breast cancer cells." (PMID 35126382, 2021). "Taken together, IL-6 not only has the potential to be a valuable predictive biomarker but also is a vital target for breast cancer treatment." (PMID 33517609, 2021). "In the various established rodent models of breast cancer, a significant decrease in IL-6 circulation is found after 20 weeks of training, leading to slower tumour growth." (PMID 35008220, 2021). "Jag1 derived from tumor cells can promote maturation of osteoclasts and osteolytic bone metastasis of breast cancer by regulating release of IL6 from osteoblasts." (PMID 34374886, 2021). "It was found that the most increasing parameters of breast cancer risk were high levels of NF-κB, TNF-α, IL-6, PCT, PTX-3, and CRP." (PMID 33776564, 2021). "Fibroblast-derived IL-6 stimulated growth and invasion of breast cancer cells in vitro through activation of STAT-3 signaling." (PMID 33809315, 2021). "Inflammatory markers such as TNF-α and IL-6 decreased after exercise training in a study of breast cancer survivors." (PMID 34638290, 2021). "IL-6 has been reported to be present in higher levels in CM2D than in CM3D and has also been associated with the stimulation of the migration of breast cancer cells by induction of AKT, MAPK and STAT3 phosphorylation." (PMID 34884877, 2021). "Supporting these finding, others demonstrated that tumor-derived Jagged 1 activates Notch signaling and increases IL-6 in osteoblasts, promotes osteoclast differentiation and thereby supports breast cancer bone metastasis." (PMID 33809315, 2021). "In samples of human breast cancer tissue, adipocytes located proximally to cancer cells were found to express IL-6 and mmp-11 via immunohistochemistry, whereas more distally located adipocytes did not." (PMID 34912237, 2021). "IL-6 also plays a critical role in transforming the dormant breast cancer cells into the actively growing tumor." (PMID 34298639, 2021). "Propofol epigenetically modulates trastuzumab resistance of breast cancer via IL-6/miR-149-5p signaling." (PMID 34789263, 2021). "Similar effects have been found in other cancers—namely, IL-6 has been shown to induce the activation of the EMT program via STAT3 activation in breast cancer and to play a role in cancer stemness of osteosarcoma cells via STAT3 activation." (PMID 34063134, 2021). "Functional polymorphisms in the IL-6 promoter that result in increased transcription of IL-6 are significantly associated with worse prognosis and decreased disease free survival (DFS) in high-risk breast cancer patients." (PMID 33483516, 2021).